LINC01097 (long independently transcribed non-coding RNA 1097)
Gene: Long non-coding RNA gene on chromosome 4 (13,526,319 to 13,534,335, reverse strand). Ensembl gene ENSG00000281202.
Diseases named in the same sentence as LINC01097 in open-access papers:
LINC01097 is named in the same sentence as 2 diseases in open-access papers, as found by Europe PMC text mining. Sharing a sentence is not in itself a finding about the gene and the disease.
LINC01097 shares sentences with these, for which no sentence is quoted: breast carcinoma (1 paper); sarcoma (1).